ROCK2 (Rho associated coiled-coil containing protein kinase 2)
Diseases named in the same sentence as ROCK2 in open-access papers (continued):
Sharing a sentence is not in itself a finding about the gene and the disease.
cancer (continued). "Amongst the various downstream effectors of Rho GTPases, the Rho associated coiled coil kinases (ROCKs) play an important role in cancer progression and ROCK2 has been shown to be present in the nuclear compartment and is involved in the cell division process." (PMID 31488179, 2019). "MiRNA-124 plays a key role in cancer cell proliferation and is epigenetically silenced in various types of cancers, and affects proliferation and motility of cancer cells by repressing ROCK2 and EZH2." (PMID 29073265, 2017). "The ROCK2 is involved in cell migration and phosphorus metabolism in SP cells, and reduced expression of ROCK2 inhibits migratory and invasive properties of cancer cells." (PMID 28467812, 2017). "Some novel isoform selective inhibitors are becoming commercially available and will serve as valuable tools for further dissecting the roles of ROCK1 and ROCK2 in cancer and other diseases." (PMID 26725045, 2016). "Recent studies have validated some of the mutations and gene variants, with an emphasis on examining those affecting the coding sequence of ROCK1 and ROCK2, and determining their impact on cancer pathogenesis." (PMID 26725045, 2016). "Numerous miRNAs involved in regulating ROCK1 and ROCK2 expression and activity have been identified in cancer tissues." (PMID 26725045, 2016). "The down-regulation of these miRNAs in cancer tissues leads to increased ROCK2 levels and increased invasion, migration, and proliferation." (PMID 26725045, 2016). "Depletion of the kinases ROCK1 and ROCK2, two known RhoC downstream effectors, similarly decreases cancer interaction with ECs." (PMID 25677806, 2015). "Studies have shown that ROCK2 is critical for cancer cell migration and invasion." (PMID 37449209, 2023). "In addition to playing an integral role in cancer development and metastasis, ROCK2 regulates the cellular contraction of smooth muscle cells and non-muscle cells." (PMID 36982538, 2023). "It has been widely demonstrated that ROCK2 is an oncogenic gene in a series of cancers; therefore, we hypothesized that ROCK2 may be involved in T4O-induced biological functions." (PMID 35322742, 2022). "On the other hand, ROCK2 was found to be a target of miR-34/449 in multiciliated cells, miR-142-3p in lymphocytes, and miR-101, miR-124, miR-138, miR-139, and miR-200b/c in cancer cells." (PMID 35043239, 2022). "Previous studies have demonstrated that ROCK2 plays a key role in the progression of PC; its suppression may inhibit cancer progression." (PMID 35322742, 2022). "Human studies indicate that ROCK2 promotes cancer growth, in addition to degrading MMP2." (PMID 34773987, 2021). "Interestingly, we found a significant reduction of cell motility and migration after treatment with AHCC and ETAS, accompanied by a downregulation of ROCK2 protein expression levels, one of the crucial players in cancer migration." (PMID 34959725, 2021). "Besides its roles in cytoskeleton reorganization in the cytosol, ROCK2 is localized in the nucleus of cancer cells, epithelial cells and neurons." (PMID 30413785, 2018). "Also in glioma, ROCK2 siRNA worked synergistically with the anti-cancer drug temozolomide, increasing the induction of apoptosis and inhibiting the migration of U251 cells." (PMID 26725045, 2016). "In addition to those miRNAs interacting with ROCK1, there are also miRNAs interacting with ROCK2 in cancers, for instance, miR-139, miR-124 and miR-101 in hepatocellular carcinoma, miR-200b/c in cholangiocarcinoma, and miR-138 in oral cancer." (PMID 26725045, 2016). "However, regulation of expression of ROCK1 and ROCK2 is often abrogated in several diseases, including several cancers." (PMID 27203208, 2016). "Our data suggest that ROCK1 and ROCK2 might act downstream of RhoC to regulate cancer cell adhesion to and transmigration across ECs." (PMID 25677806, 2015).
cancer (continued). "Furthermore, cancer associated genes (e.g., ROCK2, NFKB) are also significantly correlated with SOX2OT in SAGE libraries; which highlighted the potential function of SOX2OT in cancer progression." (PMID 26136768, 2015). "ROCK1 and ROCK2 depletion also induced a delay of cancer cell intercalation within EC monolayers." (PMID 25677806, 2015). "Together with our new results it raises the question whether NHERF2, as a modulator of ERM phosphorylation via ROCK2, may affect invasiveness of carcinoma cells." (PMID 24364877, 2013). "Additionally, investigating the broader implications of the ROCK2–Drp1 axis in other cancers may yield insights into the universal mechanisms of resistance." (PMID 40615369, 2025). "Similarly, higher expression of RhoA, ROCK1 and ROCK2 has been found in other types of cancer." (PMID 27203208, 2016). "The proteomics study confirmed the enrichment of molecules in fibronectin and the VEGF pathway in PAK4KO cancer cells, along with the upregulation of EphA2, RhoA, ROCK1, ROCK2, and components of the EPH-ephrin signalling pathway, linking to enhanced VM." (PMID 41294859, 2025). "For example, APOE, PLAU, CDK1 and MUC1 were significantly higher in TNBC tissues than in cancer-parasite tissues, whereas PDGFRB, RET, ROCK2, CCND1 and PPARA were significantly lower in TNBC tissues than in cancer-parasite tissues." (PMID 38329441, 2024). "ROCK2 is a member of the TGF‐β signaling and has been widely reported to directly regulate the EMT program in cancer." (PMID 35100495, 2022). "ROCK2, a member of ROCK family and the downstream effector of RhoA, is involved in the regulation of various cancer cell contraction, migration, invasion and survival." (PMID 33407478, 2021). "All the new compounds were evaluated for their biological properties toward extracellular matrix in rat renal proximal tubular cells, human cancer cells (K562, A549, and Huh7), EV71, ROCK2, JAK3, DDR1, and coagulation." (PMID 32876846, 2021). "This suggested that even though the expression of ROCK1 had initially not been found to differ between cells transfected with empty vector or pROR2, the ROR2-induced increase in cancer cell invasiveness involved both, ROCK1 and ROCK2." (PMID 34911552, 2021). "Taken together, these results suggested that the promotion of SW620 cancer cell invasiveness was dependent on NaV activity and indeed due to the inhibition of both ROCK-1 and ROCK-2." (PMID 32770034, 2020). "Along with the related ROCK1 and ROCK2 kinases, the MRCK proteins initiate signalling events that lead to contractile force generation which powers cancer cell motility and invasion." (PMID 25288205, 2014). "The enhancement of cancer cell migration induced by E2 was also prevented by blocking ER with ICI 182,780, by blocking c-Src with PP2, PI3K with wortmannin or ROCK-2 with Y-27632." (PMID 21818323, 2011). "Some studies have indicated the upregulation of ROCK2 in the development of cancers and noncancer diseases." (PMID 38297223, 2024). "Conversely, STUMPs and LMSs shared 47 CNAs, in particular gain/amplification of the regions containing cancer related genes as PRKDC (8q11.21; eight samples), MLL3 (7q36.1; seven samples), ROCK2 (2p25.1; six samples), CTSB (8p23.1; six samples) and STAT2 (12q13.2; five samples)." (PMID 33557274, 2021). "Although the role of ROCK2 shown in basic studies has not been questioned, only one clinical trial using the ROCK2 inhibitor AT13148 for cancer treatment was reported in 2012 (ClinicalTrials.gov identifier NCT01585701)." (PMID 32550827, 2020). "Recently developed ROCK1 and ROCK2 isoform-specific genetically modified mouse models have offered a unique opportunity to analyze in vivo physiological and pathological functions of ROCK1 and ROCK2, including cancer development and progression." (PMID 26725045, 2016). "However, in the case of miR-200b, highly expressing in cancer cells, ROCK2 was not downregulated, which additionally points to deregulated responses of pathological cells." (PMID 37261072, 2023).
cancer (continued). "Strikingly, exposure with the conditioned medium (CM) from cancer cells did not affect the glucose uptake in NSCLC/HCC-derived NPC, while it increased the expression of HK2, ROCK2, and p-MLC2 as well as lactate production in NPC as compared with untreated NPC." (PMID 34650057, 2021).
cardiovascular disease (13 papers, 2013 to 2025). "Results of current study unveil the potential of identified novel hits as promising lead compounds for ROCK2 associated with cardiovascular diseases." (PMID 37972144, 2023). "Previously, many experimental studies have revealed that increased ROCK2 activity is associated with pathogenesis of cardiovascular diseases." (PMID 26630989, 2015). "Analysis of other variations in this gene for association with cardiovascular disease and functional studies would be helpful in elucidating the involvement of ROCK2 gene in cardiovascular disease pathogenesis." (PMID 23326532, 2013). "The relationship between the ROCK2 polymorphisms and cardiovascular disease risk cannot be entirely discounted and warrants further evaluation in a large population." (PMID 23326532, 2013). "Dual ROCK1 and ROCK2 inhibitors have been linked to problematic side effects as well as some investigators also hypothesized that ROCK inhibitors would be less effective for the treatment of cardiovascular diseases." (PMID 37972144, 2023). "Therefore, it is reasonable to postulate that ROCK2 gene may also play an important role in the genetic susceptibility for cardiovascular disease." (PMID 23326532, 2013). "The current study makes use of the ROCK2 target protein and computational and medicinal chemistry methods to anticipate prospective lead compounds to inhibit ROCK2 and treat cardiovascular diseases." (PMID 37972144, 2023). "The different functions of ROCK1 and ROCK2 in the pathogenesis of cardiovascular disease have been well documented." (PMID 28684968, 2017). "Therefore, a set of novel compounds were screened that can potentially inhibit the activity of ROCK2 and help to treat cardiovascular diseases by employing In-silico techniques." (PMID 37972144, 2023). "All these results confirm the fundamental role of ROCK2 in cardiovascular diseases." (PMID 37972144, 2023). "Recently, common variants of ROCK2 have been reported to influence blood pressure, but the relationship between common ROCK2 variants and cardiovascular disease has not been extensively studied in the Chinese population." (PMID 23326532, 2013). "Despite being an attractive candidate gene, our genetic association analysis results do not support common variants in the coding region of ROCK2 to have a major effect to cardiovascular disease susceptibility." (PMID 23326532, 2013). "In this review, we focus on recent findings regarding ROCK signaling in the pathogenesis of cardiovascular disease, with a special focus on differences between ROCK1 and ROCK2 function." (PMID 26635606, 2015). "Importantly, in the context of cardiovascular disease and diabetic coronary dysfunction, both ROCK1 and ROCK2 are expressed in vascular endothelial and smooth muscle cells." (PMID 24059472, 2013). "However, we cannot rule out a biological role of ROCK2 in other populations as genetic factors influencing the pathogenesis of cardiovascular disease may differ between ethnic groups." (PMID 23326532, 2013).
infection (6 papers, 2015 to 2025). The state of being infected such as from the introduction of a foreign agent such as serum, vaccine, antigenic substance or organism. "At 4 hours post infection (hpi), we noted high ROCK2 and LIMK2 activity, both cytoskeleton regulators, possibly reflecting changes that occur during viral entry." (PMID 40502089, 2025). "After infection with LV‐NC or LV‐ROCK2, western blot analysis revealed that ROCK2 was successfully overexpressed in LV‐ROCK2‐infected bEnd.3 cells with a 3.8‐fold change." (PMID 35971637, 2022). "The luciferase activity assays showed that increased expression of miR-101 upon infection significantly affected the luciferase expressions of ROCK2 in LM9 cells." (PMID 25693145, 2015). "In the case of JEV infection, it has been shown that entry is independent of clathrin, while the regulatory proteins of actin filaments, such as RHOA, RAC1, proteins of the ARP2/3 complex, and the N-WASP family (LIMK1, PAK1, and ROCK2), are crucial for the establishment of infection." (PMID 40733526, 2025). "Moreover, numerous Ser/Thr kinases (STKs) were either increased (e.g., GRK2, ROCK2, ROCK1, PAK1) or decreased (e.g., BMP2K, TNIK, MYLK, and NRBP1) in expression in the patient samples, suggesting a widespread change in the kinome caused by pathogen infection." (PMID 38389037, 2024). "Conversely, when we performed luciferase assays using a plasmid harboring the 3’-UTR of ROCK2 mRNA, in which the binding sites for miR-101 were inactivated by site-directed mutant genesis, the luciferase activities of mutant reporters were unaffected by the simultaneous infection of miR-101." (PMID 25693145, 2015).
neurological disorders (6 papers, 2021 to 2025). "Rho-associated kinase isoform 2 (ROCK2) is an attractive drug target for several neurologic disorders." (PMID 34794469, 2021). "The RhoA/ROCK2 pathway is a critical signaling pathway in neuronal apoptosis in neurological disorders." (PMID 40808924, 2025). "ROCK2 mRNA is widely distributed all along with the central nervous system, Interfering with ROCK2 mRNA and downregulating ROCK2 expression can improve neurological diseases including neuropathic pain." (PMID 36248188, 2022). "ROCK2 has been proposed as a possible target for treatment of many neurological diseases, including Alzheimer disease, and also has putative roles in regulating cholesterol transport and cholesterol synthesis via the SREBP2 pathway." (PMID 35140266, 2022).
metabolic disorders (4 papers, 2019 to 2025). "The ROCK family including ROCK1 and ROCK2 has recently emerged as a potential therapeutic target for the treatment of metabolic disorders." (PMID 35769086, 2022). "For example, KD025 (also known as SLx-2119), a selective ROCK2 inhibitor, shows no major side effects in various clinical trials focusing on non-metabolic diseases." (PMID 35769086, 2022). "However, ROCK inhibitors have not yet been accepted for treating metabolic disorders due to potential systemic side effects, including hypotension caused by smooth muscle relaxation due to both ROCK1 and ROCK2 are similarly inhibited." (PMID 35769086, 2022).
neurodegenerative disease (4 papers, 2017 to 2025). A disorder of the central nervous system characterized by gradual and progressive loss of neural tissue and neurologic function. "Increasing with age, ROCK2 activation has been linked to neuronal cell death in Alzheimer’s brain and other neurodegenerative diseases and might be a potential therapeutic target to retard the progressive neuronal loss." (PMID 39779619, 2025). "It should be noted that ROCK2 is the dominant isoform in brain, heart, and smooth muscle cells, and, thus, inhibitors that specifically target ROCK2 are desirable in the context of neurodegenerative diseases." (PMID 32192179, 2020). "In general, ROCK2 appears to be an attractive target for the development of new therapeutic strategies, not only for NCL, but also in a wide range of more common neurodegenerative diseases to potentially halt or delay disease progression." (PMID 28963550, 2017).
kidney disease (2 papers, 2024 to 2025). "When considered alongside these previous observations, the current work implicates ROCK2 as a key molecule for the development of a wide range of kidney diseases and thus adds important public health-related findings." (PMID 38565675, 2024).
immune dysfunction (1 paper, 2024). "Although novel drugs such as BTK inhibitors, JAK inhibitors and ROCK2 inhibitors expand treatment options, irreversible fibrotic progression and severe immune dysfunction along with serious infectious complications remain challenging." (PMID 39403509, 2024).
ROCK2 also shares sentences with these, for which no sentence is quoted: Arthritis (3 papers); cardiac diseases (3); psoriasis vulgaris (3); autism spectrum disorder (2); colorectal adenocarcinoma (2); heart failure (2); infarction (2); lymphoma (2); retinopathy (2); triple-negative breast carcinoma (2); Type 1 Diabetes (2); acute liver failure (1); acute monocytic leukemia (1); adenocarcinoma (1); age (1); airway hyperresponsiveness (1); autosomal dominant polycystic kidney disease (1); benign vascular tumor (1); bipolar disorder (1); carcinoma in situ (1); cardiomyopathy (1); cataract (1); cavernous hemangioma (1); central nervous system diseases (1); cholangiocarcinoma (1); chronic kidney disease (1); chronic myeloid leukemia (1); complication (1); coronary atherosclerosis (1); coronary vasospasm (1).
A further 49 diseases each share a sentence with ROCK2 in 1 paper.